BRCA1 (BRCA1 DNA repair associated)
Diseases named in the same sentence as BRCA1 in open-access papers (continued):
Sharing a sentence is not in itself a finding about the gene and the disease.
breast cancer (continued). "The presence of BRCA1 methylation on the same BRCA1 allele in WBC and breast cancer DNA in the same patients adds strong support to the hypothesis that BRCA1-methylated tumors may arise from constitutionally BRCA1-methylated normal cells, likely initiated as an early, prenatal event." (PMID 38053165, 2023). "Literature reports for women with an inherited BRCA1 mutation a lifetime risk for breast cancer of 65–80% and 37–62% lifetime risk for developing ovarian cancer, while it reports for BRCA2 mutation carriers a lifetime risk of 45–85% for breast cancer and 11–23% for ovarian cancer." (PMID 37365514, 2023). "In breast cancer (BC), HDACs were found to be overexpressed and regulate the expression of a tumor-suppressor gene called BRCA1, which was involved in DNA repair, cell-cycle control, and cancer-cell progression." (PMID 37446915, 2023). "A genotyping study found that mutations in the BRCA1 gene are very close to the MS gene, which may be why there are more cases of breast cancer in MS patients than in non-MS cohorts." (PMID 37206644, 2023). "The somatic mutational landscape and in particular the extent of BRCA-like tumour features (BRCAness) in these familial breast cancers where germline BRCA1 or BRCA2 mutations have not been identified is to a large extent unknown." (PMID 37316882, 2023). "Therefore, it can be hypothesized that the missing BRCA1 repair proteins dramatically prevent breast cancer patients having enough ovarian reserve to enable a potential conception." (PMID 37325546, 2023). "Moreover, approximately a four-fold risk of breast cancer was reported in women with a significant family history of breast cancer but who tested negative for BRCA1 or BRCA2 variants." (PMID 37656691, 2023). "However, to high breast cancer risk associated with alterations in BRCA1 or BRCA2, both studies confirmed association of germline pathogenic CHEK2 variants with moderate breast cancer risk with odds ratio (OR) 2.5 and a cumulative lifetime breast cancer risk of 25%–30%." (PMID 37449874, 2023). "This bias may be due to the fact that the most common causative gene was BRCA2, which causes HR + breast cancer, pancreatic cancer, and prostate cancer, as opposed to BRCA1, which causes triple-negative breast cancer and ovarian cancer." (PMID 36494460, 2023). "An interesting case in the present study is represented by the detection of a MUTYH c.734G>A variant in one female patient with a personal history of breast cancer diagnosed at the age of 44 years, previously tested for BRCA1/2 variants at another institute and found to be negative." (PMID 38136276, 2023). "This is in contrast with the 70% of breast cancers in BRCA1 carriers which are triple-negative and is therefore in keeping with the hypothesis that a reduction in circulating oestrogens/progesterones following RRSO would most likely reduce the risk of hormone-sensitive tumours." (PMID 36900415, 2023). "Therefore, it provides the unprecedented opportunity to study young breast cancer cases who do not carry this founder mutation, and in effect, virtually no BRCA1/2 mutations, because of the very low prevalence of other BRCA1/2 mutations in the population." (PMID 38036573, 2023). "Among individuals of AJ ancestry, most breast cancers are due to three BRCA1/2 founder mutations (BRCA1: 185delAG [c.68_69del], 5382insC [c.5266dup]; BRCA2: 6174delT [c.5946del]); while in the Mexican population the founder mutation BRCA1 ex9-12del has a high frequency." (PMID 36845387, 2023).
breast cancer (continued). "To investigate which BRCA1/2-independent mechanisms drive spontaneous resistance in vivo, we combine molecular profiling with functional analysis of HR of matched PARPi-naive and PARPi-resistant mouse mammary tumors harboring large intragenic deletions that prevent reactivation of BRCA1/2." (PMID 37209095, 2023). "While rare, high-penetrance mutations, such as BRCA1 and BRCA2, account for a minority of breast cancer cases, recent advancements in genomic sequencing technologies have opened new avenues for uncovering additional genetic modifiers that influence breast cancer risk." (PMID 38156855, 2023). "The most significant genes implicated in hereditary breast cancer are the BRCA1 and BRCA2 genes, and pathogenic mutations in these genes together accounting for about 30% of high-risk breast cancer families and explain about 15% of the breast cancer familial relative risk." (PMID 38020349, 2023). "Similarly, the BRCA1 tandem duplication of exons 18 to 20 carried by patient 20X0131 resulted in a pseudo circular RNA joining exon 20 to duplicated exon 18 and was found in the patient’s breast-cancer tissue sample." (PMID 37046838, 2023). "However, they concluded that there is currently insufficient evidence to propose individualized recommendations for dietary habits or weight management specifically for women with BRCA1 and BRCA2 germline variants compared to the general population regarding breast cancer risk reduction." (PMID 37628558, 2023). "We are going to focus our scientific interest on patients with early-onset cardiovascular diseases, hematological patients with suspected but not confirmed MDS, and breast cancer patients with BRCA1/2 germline mutations who have received chemotherapy and/or PARP inhibitor therapy." (PMID 38162500, 2023). "It has been largely demonstrated that pathogenic mutations in the BRCA1 and BRCA2 genes increase the risk of developing breast cancer, respectively, by 65% and 45%, and are responsible for 90% of all hereditary BC cases." (PMID 37111307, 2023). "Germline pathogenic variants (PVs) in the tumor suppressor genes BRCA1 (MIM#113705) and BRCA2 (MIM#600185) confer a cumulative lifetime risk of developing breast cancer (BC) by age 80 of 72% and 69%, respectively." (PMID 37168384, 2023). "Thus, NORE1A forms a tumor suppressor complex with BRCA1 and may play an important role in connecting Her2 to BRCA1 regulation to modulate the senescence response to oncogenic lesions in breast cancer." (PMID 37627161, 2023). "BC risk factors may include a median age at menarche and first pregnancy, menopause at an older age, elevated estradiol levels, stress, Klinefelter syndrome, obesity, coffee intake, radiation exposure, gynecomastia, a family history of breast cancer, as well as BRCA2 and BRCA1 mutations." (PMID 37079213, 2023). "Due to the decreased cost of gBRCA testing and the promising efficacy of olaparib therapy to improve survival in patients with breast cancer and BRCA1/2 PVs, it is essential to examine whether gBRCA testing is appropriate for all patients with TNBC and HR-positive HER2-negative breast tumours." (PMID 36564566, 2023). "While screening protocols exist for patients who are considered high risk (i.e., known carrier of a BRCA1/2, strong family history, or previous thoracic radiation), average-risk young females are not routinely screened for breast cancer, potentially contributing to their later-stage diagnoses." (PMID 37999115, 2023). "However, we noted that BRCA1 mutated cases displayed a higher incidence of triple‐negative (TN) breast cancer than in BRCA2 cases, regardless of ALDH2 genotypes." (PMID 36345163, 2023). "A human with biallelic BRCA1 mutations was first reported in 1995, in a woman with breast cancer at age 32 and no other clinical features, described as homozygous for a high penetrance breast/ovarian cancer-associated mutation, but this report was subsequently found to be inaccurate." (PMID 38146508, 2023).
breast cancer (continued). "The finding that the co-occurrence of BRCA1/2 mutations and a HER2-positive status is associated with worse OS in patients with early or locally advanced breast cancer may be proof of concept that a combined pharmacological intervention directed to these targets could be synergistic." (PMID 37444415, 2023). "Therefore, targeting the H19/ILF2/BRCA1 axis might modulate therapeutic approaches in breast cancer." (PMID 37298108, 2023). "In a study of 60 breast cancers, stratified by familial history and known BRCA status, there were significantly higher levels of VEGF and Angiopoietin-1 and Angiopoietin-2, two other angiogenic factors involved in vessel remodelling in patients with BRCA1/2 mutations." (PMID 36831687, 2023). "S100A9-CXCL12 signaling activation could enhance cancer progression and trigger the expansion and accumulation of myeloid-derived suppressor cells (MDSCs), producing a tumor-permissive microenvironment and endowing resistance to ICB in BRCA1-mutant breast cancers." (PMID 37564657, 2023). "A recent study examined the association between the isoflavone intake and breast cancer risk by molecular subtype in 1,709 Korean females featuring a high risk of hereditary breast cancer (i.e., BRCA1/2 mutation carriers and non-carriers with family history and early-onset breast cancer)." (PMID 36829927, 2023). "In contrast, BRCA1-basal-like breast cancers might originate from basal stem cells." (PMID 36632469, 2023). "Overall, it seems that clinical research on PARP inhibitors is ongoing, and the benefits of this approach might not be limited to HER2-negative breast cancer with BRCA1 and 2 mutations." (PMID 37759706, 2023). "Another mechanism of action promoting BRCA1-associated postmenopausal breast cancer may be the lack of suppression of aromatase." (PMID 37340476, 2023). "While BRCA1/2-related breast cancers are known to occur at earlier ages than sporadic breast cancers, preliminary data suggest that age at diagnosis observed in patients carrying PVs in other breast cancer risk-associated genes may be more similar to age at diagnosis of sporadic breast cancers." (PMID 37084156, 2023). "Similar trends were observed for unaffected women, where BRCA1 (OR 2.34, 95% CI 2.13, 2.56) and BRCA2 (OR 1.25, 95% CI 1.16, 1.35), were associated with a significant increase in risk among women with a relative diagnosed ≤ 45 versus > 45 years of age with breast cancer." (PMID 37084156, 2023). "Given the histopathological differences between the breast cancer 1 gene (BRCA1) mutated and non-BRCA1-related tumors, a widely recognized prognostic biomarker for BRCA1-positive BC remains to be found." (PMID 36614323, 2023). "Vitamin supplement use is very popular among Canadian women, but the extent to which consuming vitamin D supplements may affect breast cancer risk in BRCA1 or BRCA2 mutation carriers is not known." (PMID 37345127, 2023). "BRCA1/2 mutation carriers can have up to a six-fold higher lifetime risk of developing breast cancer, and approximately a four-fold increased risk of developing a second primary contralateral breast cancer compared to women without this mutation." (PMID 36834079, 2023). "To study the specificity of this MBC PV/LPV profile, we examined whether variants in the same genes could be detected in a female breast cancer (FBC) cohort without BRCA1/BRCA2/PALB2 PV/LPV." (PMID 37762649, 2023). "Therefore, we hypothesized that the ALDH2 genotypes may impact breast cancer development in BRCA1/2 mutant carriers." (PMID 36345163, 2023). "For example, Medicare currently pays $1117.98 for a hereditary breast cancer panel (CPT code 81432) while reimbursing $1824.88 for BRCA1/2 gene analyses alone (CPT code 81162), which might be combined with $584.23 under code 81164, a test for structural BRCA1/2 rearrangements." (PMID 37435610, 2023).
breast cancer (continued). "Besides the relatively well-documented hereditary cases explained partly by BRCA1 and BRCA2 gene mutations, alterations of several other genes have been identified as susceptibility factors for breast carcinoma, but a significant fraction of the heritability of the disease is still unexplained." (PMID 37239898, 2023). "Although the patient was positive for a BRCA1 (breast cancer 1, early onset) gene mutation and had a history of breast cancer on her mother’s side of the family, no tumour was initially found despite extensive diagnostic work-up, including regular screening with whole-body 18FDG-PET." (PMID 35907972, 2022). "Although the treatment potential for PARP inhibitors in wild-type BRCA patients is unknown, both preclinical and in vivo studies are showing promise for their efficacy in breast cancers without BRCA1/2 mutations." (PMID 35158750, 2022). "EGFR and BRCA1 may also affect the function of AR in breast cancers." (PMID 35053220, 2022). "Characterising pathogenic variant type in BRCA1, and future screening for deletions overlapping SULT1A1, may produce variables to be incorporated with other modifying factors to develop a more comprehensive model of breast cancer risk." (PMID 36203093, 2022). "However, in breast cancer cell lines, this combination suppressed cell proliferation by increasing the mRNA and protein levels of Brca1 due to decreased promoter methylation, the downregulation of both DNMT1 expression and miR-29b, and the upregulation of TET1 and DNMT3." (PMID 35327559, 2022). "These CpGs were selected based on methylation scores with median methylation level at least 0.01 greater in histologically normal breast tissue of BRCA1/2 mutation carriers (n = 14) compared to cancer-free women with no family or personal history of breast cancer (n = 14), (DNAme Set 1)." (PMID 35701800, 2022). "We then demonstrated a small but statistically significant increase in mutation frequency in mammary epithelial cells isolated from the breast of BRCA1/2 mutation carriers as compared with those obtained from age-matched controls with no genetically increased risk for breast cancer." (PMID 35025760, 2022). "BRCA1 mutations dramatically increase the risk of developing breast cancer, which suggests the loss of Beclin-1 is not likely to be the primary cause of breast cancer." (PMID 35884904, 2022). "However, only two samples had mutations located at the important coding region of BRCA1/2, indicating that the contribution of BRCA1/2 to cervical cancer may be smaller than that in breast cancer or ovarian cancer." (PMID 35205332, 2022). "Here, the association of EZH2 mRNA expression with BRCA1-mutant breast cancer was further evaluated using the TCGA BRCA whole exome sequencing data set (n = 526) confirming the increased expression of EZH2 in BRCA1-mutant (n = 18), compared to BRCA1-wild type breast cancer (n = 508) (p = 0.0003)." (PMID 35715861, 2022). "However, despite having these features, BRCA1 deficient breast cancers do not show a significantly improved response to ICB compared with BRCA1 proficient breast cancers." (PMID 35304461, 2022). "Finally, the well-known triple-negative phenotype of BRCA1 tumors could also result in more referrals for genetic testing for BRCA1 versus BRCA2 breast cancer patients." (PMID 35805038, 2022). "Thus, in 2010, a study was conducted of patients with locally advanced breast cancer with and without BRCA1 and -2 mutations." (PMID 36613648, 2022). "Hormone receptor positivity in mammary tumors was not correlated to the presence or absence of the Brca1 allele, but instead to inhibition of Rbf via expression of the TgK18GT121 allele, pointing to differences in Rb pathway regulation as a key determinant between HR-positive and HR-negative models." (PMID 36333737, 2022).
breast cancer (continued). "In our efforts to identify drugs that might inhibit BRCA1-deficient tumor growth and metastasis, we found that paclitaxel or docetaxel treatment can reverse the expression pattern of ATP11B and PTDSS2 in breast cancers and significantly inhibit cancer metastasis." (PMID 35025764, 2022). "HBOC is caused by pathogenic variants in BRCA1/2 which confer substantially elevated risks for female breast cancer, ovarian cancer, and male breast cancer (in particular for BRCA2 carriers), in addition to increased risks for pancreatic cancer, prostate cancer, and melanoma." (PMID 36353115, 2022). "However, it is currently unclear whether there is any linkage between these E3 ligases and BRCA1 in breast cancer tumorigenesis." (PMID 35280675, 2022). "Examples of extensive genomic databases like deCODE genetics Iceland show that holding this data has numerous ethical implications, e.g., how to deal with the stored information on carriership of the breast cancer genes BRCA-1 and BRCA-2 and whether to inform and screen affected individuals." (PMID 35323196, 2022). "We analyzed mutation data of the breast cancer samples with and without “pathogenic” or “likely pathogenic” BRCA1 mutation as determined by ACMG 2015 criteria (referred to as BRCA1-positive and -negative, respectively) that were available on three public cancer databases: TCGA, ICGC, and COSMIC)." (PMID 36298462, 2022). "Since the number of patients in each group was low, the survival analysis suggested that the trend of having a mutation of the BRCA1/2 gene or not could impact overall survival in breast cancer and ovarian cancer patients." (PMID 35205313, 2022). "Between genetic risk factors, mutations to the breast cancer gene (BRCA) (BRCA1 and BRCA2) are thought to be able to give approximately from 5% to 10% of all BC." (PMID 36412681, 2022). "Approximately 60% of BRCA1-associated breast cancers are triple negative (TNBC), i.e., negative for estrogen receptor (ER), progesterone receptor (PR), and human epidermal growth factor receptor 2 (HER2); these are very aggressive and high-grade cancers with a poor prognosis." (PMID 35025764, 2022). "Analysing mutations with correct and reliable genetic testing in the significant genes (BRCA1 and BRCA2) and less commonly mutated genes (such as PTEN) and subsequent genetic counselling in high‐risk women can be beneficial in the early detection and/or prevention of breast cancer development." (PMID 35762299, 2022). "Moreover, patients with triple-negative breast cancer (TNBC) were more likely to harbor BRCA1 mutations than those with HR+ or HER2+ breast cancer (P=0.006)." (PMID 35494038, 2022). "Given the high risk of breast cancer for women in the general population, in large families where a pathogenic variant of BRCA1 is segregating, some women may be affected without carrying the variant." (PMID 36013215, 2022). "BRCA1 and BRCA2 germline mutations are associated with an aggressive BC course (the triple-negative breast cancer subtype especially) and advanced OC." (PMID 35409996, 2022). "Interestingly, PIK3CA mutations, which were the top mutation in BRCA1-negative and unspecified breast cancer, were found in the lower frequencies of 13.33–16.67% and were not among the top mutated genes in the BRCA1-positive group." (PMID 36298462, 2022). "Collectively, the evidence supports therapeutic inhibition of the RANK pathway for the primary prevention of BRCA1-associated breast cancer, which may generate unique prevention strategies (without prophylactic surgery) and enhance quality of life." (PMID 35418083, 2022).